LGI1 (leucine rich glioma inactivated 1)
Diseases named in the same sentence as LGI1 in open-access papers (continued):
Sharing a sentence is not in itself a finding about the gene and the disease.
encephalitis (continued). "Collectively, these functional and structural alterations in cortical regions are associated with memory, motor, and cognitive dysfunction in anti-LGI1 encephalitis." (PMID 40688080, 2025). "This hypermetabolic profile is viewed as characteristic of anti‐LGI1 encephalitis and reflects active inflammation." (PMID 41153078, 2025). "Patients with anti-LGI1 encephalitis often present with focal seizures, particularly of the faciobrachial dystonic type, in addition to complex focal seizures accompanied by cognitive or autonomic features." (PMID 40131535, 2025). "Since then, the LGI1-ANTibody encephalitis outcome RatiNg scale (LANTERN) has been developed, although other autoimmune encephalitides remain without a validated outcome score." (PMID 40886242, 2025). "Anti-leucine-rich glioma-inactivated 1 (anti-LGI1) encephalitis is a rare autoimmune encephalitis (AE) characterized by cognitive impairment, psychiatric symptoms, refractory hyponatremia, and seizures, particularly faciobrachial dystonic seizures (FBDSs)." (PMID 40271344, 2025). "Anti-LGI1 encephalitis is an immune-mediated autoimmune disorder characterized by memory impairment, epileptic seizures, FBDS, psychiatric and behavioral disturbances, autonomic dysfunction, hyponatremia, and HHCY." (PMID 41473232, 2025). "In this study, we identified ictal cold shiver as a potential manifestation of autoimmune limbic encephalitis that occurred with greater frequency than anticipated, particularly in anti-LGI1-related encephalitis." (PMID 40958893, 2025). "As the second most prevalent AE subtype following anti-N-methyl-D-aspartate receptor (NMDAR) encephalitis, anti-LGI1 encephalitis accounts for approximately 30% of limbic encephalitis cases." (PMID 40519939, 2025). "It should be noted that for prediction of a favourable mRS alone, the wide confidence interval suggests some uncertainty as to the exact effect size of an anti-LGI1 Ab-mediated encephalitis diagnosis in a broad cohort of AE patients." (PMID 40281286, 2025). "The age of onset for anti-NMDAR encephalitis ranges from 0.6 to 85 years, for anti-LGI1 encephalitis from 30 to 80 years, and for anti-CASPR2 encephalitis from 46 to 77 years." (PMID 40131535, 2025). "Patients with anti-LGI1 encephalitis usually respond well to one of the first-line immunotherapies, including IVMP, plasma exchange, or intravenous immunoglobulins (IVIgs)." (PMID 41164023, 2025). "Importantly, we propose that this LGI1‐specific metabolic pattern could serve as a predictive biomarker for assessing acute disease severity and cognitive function in anti‐LGI1 encephalitis, with significant implications for early detection and risk stratification." (PMID 41399525, 2025). "In multivariable analysis, a diagnosis of anti-LGI1 Ab-mediated encephalitis compared to other subtypes (OR 4.46; 95% CI 1.55, 12.80; p = 0.006) was associated with a better 12-month mRS (mRS ≤ 2)." (PMID 40281286, 2025). "This sex distribution aligns with previous studies, which have consistently reported a male predominance of approximately 60–70% among patients with anti-LGI1 encephalitis." (PMID 41473232, 2025). "Along with the N-methyl-D-aspartate receptor (NMDAR), leucine-rich-glioma-inactivated-1 (LGI1) and contactin-associated-protein-like-2 (CASPR2) are the three most common target antigens in antibody-mediated encephalitis." (PMID 40131535, 2025). "We conducted a comprehensive analysis of the relationship between 18F‐FDG‐PET metabolic patterns and the clinical manifestations and progression of anti‐LGI1 encephalitis." (PMID 41399525, 2025). "Previous studies on anti-LGI1 encephalitis have primarily reported that its main clinical manifestations include memory impairment, seizures, psychiatric and behavioral abnormalities, FBDS, and hyponatremia." (PMID 41473232, 2025). "Anti-LGI1 encephalitis is typically unrelated to malignancies, despite the possibility that it is a paraneoplastic condition." (PMID 40271344, 2025).
encephalitis (continued). "Conventional MRI often reveals T1/T2 hyperintensities in the medial temporal lobe, hippocampus, and basal ganglia in anti-LGI1 encephalitis patients." (PMID 40688080, 2025). "In LGI1 encephalitis, FBDS typically precede the onset of cognitive and psychiatric symptoms by some months." (PMID 40407616, 2025). "Notable inward shape deformations were detected in patients with anti-LGI1 encephalitis compared with normal controls in the bilateral hippocampus, NAc, caudate, and thalamus." (PMID 40688080, 2025). "It has been reported in the literature that the patient with overlapping LGI1 antibodies showed left faciobrachial dystonic seizures, which represent the primary clinical manifestation of LGI1 antibody encephalitis." (PMID 40028323, 2025). "Anti-LGI1 antibody-mediated encephalitis relative to other subtypes (OR 4.46; 95% CI 1.55, 12.80; p = 0.006) was associated with a better 12-month mRS." (PMID 40281286, 2025). "Twenty-three (3%) of them fulfilled the diagnostic criteria for possible AIE, and 9 (1%) had antibody-positive AIE (five anti-NMDAR encephalitis, two anti-LGi1 encephalitis, one anti-Ma2 encephalitis and anti-CV2 encephalitis)." (PMID 41074474, 2025). "We therefore investigated the shape abnormalities of subcortical structures and their morphological correlations in patients with anti-LGI1 encephalitis." (PMID 40688080, 2025). "Overall, 18F‐FDG PET uncovers a NAc‐centered metabolic network that parallels disease severity in anti‐LGI1 encephalitis." (PMID 41399525, 2025). "Video-EEG recordings of juvenile rats uncovered two peaks of seizure frequency during the 7-day antibody infusion period resembling the natural progression of seizures in human anti-LGI1 encephalitis." (PMID 39984135, 2025). "Significant inward shape deformations were observed in the limbic system and basal ganglia in patients with anti-LGI1 encephalitis compared to healthy controls." (PMID 40688080, 2025). "Despite the favorable response to initial treatment, relapse has been reported in 16.2%, 27%, and 35% in different populations of anti-LGI1 encephalitis." (PMID 41164023, 2025). "The results showed that for the anti-NMDAR antibody encephalitis cohort, the AUC was 0.795 (95% CI 0.709–0.881), p value <0.001, and for the anti-LGI1 encephalitis cohort, the AUC was 0.878 (95% CI 0.784–0.972), p value <0.001." (PMID 40170898, 2025). "Additional research is necessary to clarify the relationship between ictal cold shiver and anti-LGI1 encephalitis." (PMID 40958893, 2025). "The first group comprised 238 patients with anti-NMDAR encephalitis, while the second group consisted of 150 patients with anti-LGI1 or anti-CASPR2 encephalitis (anti-LGI1 107 patients, anti-CASPR2 43 patients)." (PMID 40131535, 2025). "Previous research has documented structural abnormalities in the hippocampus and temporal lobe among anti-LGI1 encephalitis patients." (PMID 40919049, 2025). "We employed ALFF-based multivoxel analysis and two-sample t-tests to pinpoint distinct brain regions exhibiting significant differences between anti-LGI1 encephalitis patients and healthy controls." (PMID 40919049, 2025). "Among the case group, 12 patients had anti-NMDAR encephalitis, one had anti-GABAB receptor encephalitis, one had anti-LGI1 antibody encephalitis, and 22 had probable antibody-negative AE." (PMID 41441218, 2025). "In conclusion, this study demonstrates that the shapes of subcortical structures serve as reliable biomarkers indicating damage to the limbic system and basal ganglia in patients with anti-LGI1 encephalitis." (PMID 40688080, 2025). "Accumulating evidence suggests that 18F‐FDG PET/CT outperforms MRI for detecting acute anti‐LGI1 encephalitis." (PMID 41399525, 2025). "Anti-LGI1 encephalitis is an autoimmune disorder of the brain, characterized by subacute cognitive impairment, faciobrachial dystonic seizures, and hyponatremia." (PMID 41311428, 2025).
encephalitis (continued). "This study included 31 patients diagnosed with anti-LGI1 encephalitis and 31 group-matched healthy controls." (PMID 40688080, 2025). "Our results suggest anti-LGI1 Ab-mediated encephalitis carries a better functional and clinical prognosis than other forms of AE." (PMID 40281286, 2025). "Anti-leucine-rich glioma-inactivated-1 (LGI1) encephalitis is a synaptic autoimmune disorder mediated by LGI1-IgG." (PMID 40703404, 2025). "Comparisons of shape deformations of subcortical brain regions between patients with anti-LGI1 encephalitis and normal controls." (PMID 40688080, 2025). "The anti-NMDAR encephalitis was diagnosed in 5 patients while anti-LGI-1 encephalitis and GAD-65 encephalitis were present in 1 and 2 patients, respectively." (PMID 40895099, 2025). "In patients with anti-LGI1 Ab-mediated encephalitis, mesial temporal lobe hyperintensity is known to be associated with cognitive impairment." (PMID 40281286, 2025). "Studies suggest that corticosteroids tend to exhibit better immunosuppressive effects than IVIg in various IgG4-related autoimmune diseases (IgG4-AID) (e.g., anti-LGI1 encephalitis)." (PMID 40519920, 2025). "The clinical diagnosis of anti-LGI1 encephalitis relies on a combination of characteristic clinical manifestations, supportive diagnostic tests, and antibody detection." (PMID 40688080, 2025). "In recent years, advances in antibody detection techniques have facilitated the accurate diagnosis of an increasing number of anti-LGI1 encephalitis cases." (PMID 41473232, 2025). "The volumes in the right hippocampus and right nucleus accumbens in anti-LGI1 encephalitis group were significantly decreased than that of the control group." (PMID 40688080, 2025). "Our study contributes to this understanding by presenting inward shape deformations of the hippocampus in patients with anti-LGI1 encephalitis compared with healthy controls." (PMID 40688080, 2025). "The study included 27 patients with anti-LGI1 encephalitis and 28 age- and sex-matched normal controls." (PMID 40919049, 2025). "LGI1-Ab encephalitis is increasingly being recognized as the most common form of AE in adults and typically affects elderly men with a median age at onset of 65–66 years." (PMID 40274643, 2025). "One patient had no documented relevant clinical symptoms, while the other displayed the typical clinical presentation of anti-LGI1 encephalitis, with a baseline MOG-IgG titer of 1:100." (PMID 40703404, 2025). "This patient with anti-LGI1 encephalitis showed a favorable response to the first-line immunotherapy with a combination of IVMP and PE; however, psychobehavioral symptoms relapsed one month after the initial treatment and five months from the onset." (PMID 41164023, 2025). "In this study, we investigated abnormalities in effective connectivity in anti-LGI1 encephalitis patients using spDCM and low-frequency oscillation amplitude analysis." (PMID 40919049, 2025). "Leucine-rich glioma-inactivated 1 (LGI1) antibody encephalitis is among the more common subtypes of AE, primarily affecting older male patients." (PMID 40718213, 2025). "The untreated patients were excluded from the multivariate analysis in both the anti-NMDAR encephalitis and the anti-LGI1/CASPR2 encephalitis groups due to their even smaller and therefore even more inhomogeneous size." (PMID 40131535, 2025). "This study investigated subcortical shape abnormalities in patients with anti-LGI1 encephalitis using advanced shape analysis." (PMID 40688080, 2025). "In this report, we present a case of LGI1 encephalitis initially manifesting as isolated FBDS, occurring in close temporal association with the discovery of lung adenocarcinoma." (PMID 40407616, 2025). "Encephalitis with antibodies to leucine-rich glioma-inactivated 1 (LGI1-Ab-E) is a common form of autoimmune encephalitis, presenting with seizures and neuropsychiatric changes, predominantly in older males." (PMID 39454566, 2025).
encephalitis (continued). "These test results suggested a reduction in LGI1 antibody titers in the follow-up samples; however, a possible relapse of encephalitis was suspected based on psychobehavioral deterioration, as evidenced by the 11-point increase in the CASE score." (PMID 41164023, 2025). "In autoimmune etiologies, such as anti-leucine-rich glioma-inactivated 1 (LGI1) encephalitis, seizures are often refractory to ASMs alone but respond to immunotherapy." (PMID 40563808, 2025). "Forty‐seven patients with anti‐LGI1 encephalitis and 25 healthy controls underwent 18F‐FDG PET/CT, and voxel‐wise comprised to identify regional metabolic alterations." (PMID 41399525, 2025). "They did not significantly differ by demographics or clinical features and displayed a classical LGI1-Ab-E phenotype: median age 64–66 years, 30%–31% female, and 95% presenting with encephalitis or seizures." (PMID 39454566, 2025). "Clinically, anti‐LGI1 encephalitis often presents with persistent long‐term memory impairment during the recovery phase, which has been linked to hippocampal metabolic abnormalities." (PMID 41399525, 2025). "One of the discrepant samples (positive cCBA and negative hCBA) was drawn from a 77-year-old man with a typical limbic encephalitis compatible with anti-LGI1 aAbs encephalitis (confusion, seizures, and Flair hyperintensity of medial temporal lobes on MRI)." (PMID 40303411, 2025). "The localized involvement of the thalamus in our findings offers valuable insights into the diagnosis and treatment of anti-LGI1 encephalitis." (PMID 40688080, 2025). "Based on a cohort of 87 patients diagnosed with anti-LGI1 encephalitis, the present study systematically analyzed their clinical characteristics to enhance understanding of this rare autoimmune neurological disorder." (PMID 41473232, 2025). "This study identified notable outward shape deformations in the bilateral amygdala of patients with anti-LGI1 encephalitis." (PMID 40688080, 2025). "So, patients with anti-NMDAR encephalitis present a higher median mRS at 3 months compared to patients with anti-LGI1/CASPR2 encephalitis, although 70% of them recovered mRS <2 at 12 months." (PMID 39944213, 2025). "As a further element, the patient was found to be a DRB1*07 carrier, which is present in approximately 90% of patients with anti-LGI1 encephalitis." (PMID 40407616, 2025). "For example, in patients with anti-LGI1 encephalitis, long-term low-dose corticosteroid maintenance following acute-phase seizures has been reported to prevent seizure recurrence." (PMID 41306289, 2025). "A diagnosis of anti-LGI1 Ab-mediated encephalitis when compared to all other patients with AE predicted a better twelve-month functional outcome." (PMID 40281286, 2025). "The neuroimaging landscape of LGI1 antibody encephalitis is continually expanding, with anatomical and functional MRI (fMRI) studies revealing alterations in cortical connectivity and volume." (PMID 40688080, 2025). "Tumors have been implicated in producing autoantibodies by expressing neuronal antigens, leading to various forms of AE, including anti-NMDAR encephalitis or leucine-rich glioma-inactivated 1 (LGI1) antibody encephalitis." (PMID 41441218, 2025). "DLPFC‐mediated cognitive regulation plays a crucial role in the neural circuitry of cognitive dysfunction in acute anti‐LGI1 encephalitis." (PMID 41399525, 2025). "Leucine-rich glioma-inactivated 1 (LGI1) encephalitis is a form of autoimmune encephalitis (AE) that presents with memory loss, faciobrachial dystonic seizures (FBDSs), disorientation, psychiatric symptoms, and hyponatremia." (PMID 40271344, 2025). "In conclusion, we describe a unique case of anti-NMDAR encephalitis with co-occurring LGI1 antibodies presenting with predominant psychosis and seizures symptoms." (PMID 39820999, 2025). "Anti–leucine-rich glioma-inactivated 1 (anti-LGI1) encephalitis is an autoimmune disorder characterized by antibodies targeting the LGI1 protein." (PMID 40688080, 2025).
encephalitis (continued). "Two patients received LGI1-Ab encephalitis diagnosis during the relapse, when LGI1-Abs were detected in both the serum and CSF." (PMID 38603771, 2024). "Since the recognition of autoimmune limbic encephalitis (ALE) in the mid-2000s, such as anti-N-methyl-D-aspartate receptor (NMDAR) and leucine-rich glioma-inactivated 1 (LGI1) encephalitis, the existence of HE has become more questionable." (PMID 38861245, 2024). "Another limitation is the relatively modest sample size; nonetheless, given that LGI1-Ab encephalitis is a rare disease, the present cohort of relapsing patients considerably adds to the available literature." (PMID 38603771, 2024). "CSF was collected from three patients with either LGI1 (n = 2) or CASPR2 (n = 1) antibody encephalitis at their disease presentation, 21 to 1,041 d after the onset of frequent focal seizures and memory disturbances typical of their disorders." (PMID 38319973, 2024). "Clinical characteristics of both groups were compared, including differences between anti-NMDAR and anti-LGI1 encephalitis within the seizure group." (PMID 39539648, 2024). "In anti-LGI1 encephalitis, abnormal metabolism occurs in different brain regions, including the medial temporal, hippocampus, and cerebellum." (PMID 39072315, 2024). "Anti‐leucine‐rich glioma‐inactivated protein 1 (anti‐LGI1) encephalitis usually presents with mild faciobrachial dystonic or focal seizures followed by memory impairment." (PMID 39315845, 2024). "There were no abnormalities in biochemical or imaging studies; hence, the diagnosis of relapse of anti-LGI1 encephalitis was delayed." (PMID 39867015, 2024). "The AMPAR loss is believed to directly contribute to the memory deficits observed in individuals with anti-LGI1 encephalitis." (PMID 38698867, 2024). "We conducted a detailed analysis of 312 AE patients from Xuanwu Hospital, tracking various subtypes such as anti‐NMDAR and anti‐LGI1 encephalitis, and assessed their response to immunotherapy over a 24‐month period." (PMID 39315845, 2024). "Based on the AE diagnostic criteria, the patient was definitively diagnosed with anti-LGI1 encephalitis." (PMID 39421741, 2024). "In this study, we describe and clinically characterize the relapses in a cohort of relapsing patients with LGI1-Ab encephalitis and investigate potential predictors of relapse." (PMID 38603771, 2024). "First reported in 2010, anti-LGI1 encephalitis is the second most common autoimmune encephalitis after anti-NMDAR encephalitis and the most common etiology of limbic encephalitis." (PMID 38327544, 2024). "Patient‐reported quality‐of‐life (QoL) and carer impacts are not reported after leucine‐rich glioma‐inactivated 1‐antibody encephalitis (LGI1‐Ab‐E)." (PMID 38303486, 2024). "It is plausible that this structural hippocampal damage underlies the residual memory deficits after the active phase of anti-LGI1 encephalitis and possibly the rare development of epilepsy." (PMID 39105896, 2024). "The median time from the LGI1-Ab encephalitis onset to the first relapse was 23.9 months (range: 4.9–110.1, IQR: 17.8); 18/33 (55%) relapses occurred more than 2 years after onset." (PMID 38603771, 2024). "The isolated presence of FBDS, unremarkable brain MRI and normal serum sodium levels in early stages of anti-LGI1 encephalitis indicate a circumscribed brain area affected." (PMID 37278857, 2024). "Typically, most patients with LGI1-Ab encephalitis have a good prognosis as measured by the mRS,1,2,9,12,21 but in this study, a third of the patients who stabilized after the relapse had a poor outcome at the last follow-up." (PMID 38603771, 2024). "Anti-LGI1 encephalitis is highly specific for FBDS, although it is only found in a small percentage of patients." (PMID 39734683, 2024). "Anti-leucine-rich, glioma-inactivated protein 1 (LGI1) encephalitis is one of the more common forms of autoimmune encephalitis." (PMID 39105896, 2024).